TLR4 (toll like receptor 4)
Diseases named in the same sentence as TLR4 in open-access papers (continued):
Sharing a sentence is not in itself a finding about the gene and the disease.
gastric cancer (continued). "Third, in this study, only the changes in TLR4 in gastric cancer tissues were studied, and other proteins involved in signal transduction pathways were not studied." (PMID 38720250, 2024). "Our research results indicate that LDN reduces the expression level of TLR4 in gastric cancer tissue and increases the expression level of IL-6 in gastric cancer tissue." (PMID 38720250, 2024). "As cited above, TLR4 polymorphisms have been linked to an increased risk of developing certain types of cancer, including CRC and gastric cancer." (PMID 37998389, 2023). "Li5 showed that lipopolysaccharide stimulation induced the expression of CXCR7 in gastric cancer through toll-like receptor 4/myeloid differentiation factor 2 (TLR4/MD-2) signaling, thereby promoting the proliferation and migration of SGC7901 cells." (PMID 37057293, 2023). "Propionibacterium acnes (P. acnes) promotes gastric cancer progression by promoting M2 polarization of macrophages through Toll-like Receptor 4 (TLR4)/phosphoinositide 3-kinase (PI3K)/protein kinase B (AKT) signaling." (PMID 36341377, 2022). "The ASCL2 shows a negative correlation with H. pylori-induced gastrointestinal inflammation, uses resistin as a regulator of inflammation, activates TLR signaling and TLR4 cascade, and positively correlates with gastric cancer by GSEA." (PMID 36008864, 2022). "Gastric cancer cell-derived exosomes induce neutrophil autophagy and induce neutrophil N2 polarization via HMGB1/TLR4/NF-κB signaling to promote gastric cancer cell migration." (PMID 36365103, 2022). "In gastric cancer, hypomethylation of the TLR4 promoter also induces TLR4 expression and NF-κB signalling." (PMID 34226490, 2021). "Some studies assessing the role of polymorphisms in TLR2, TLR4, TLR5, NOD1 and NOD2 in gastric cancer have been published." (PMID 33879265, 2021). "The aim of this study was to assess if polymorphisms of TLR2, TLR4, TLR5, NOD1 and NOD2 genes are associated with gastric cancer, in particular in individuals infected with H. pylori." (PMID 33879265, 2021). "LPS stimulation induces the expression of CXCR7 in gastric cancer and promotes the proliferation and migration of gastric cancer cells through the TLR4/MD-2 signaling pathway." (PMID 33897888, 2021). "The aim of our study was to assess the association of common polymorphisms in TLR2, TLR4, TLR5, NOD1 and NOD2 with gastric cancer in H. pylori infected subjects." (PMID 33879265, 2021). "Helicobacter pylori (HP) and its lipopolysaccharide (LPS), which is a component of its outer membrane, significantly augmented gastric cancer cell growth via the LPS-Toll like receptor 4 pathway." (PMID 32630328, 2020). "The TLR4 expression is upregulated in gastric cancer tissues and confers LPS responsiveness to augment the activation of NF-κB and IL-8 promoter upon stimulation with H. pylori LPS." (PMID 33217986, 2020). "In gastric cancer, lipopolysaccharide induces the TLR4 (toll-like receptor 4)/MD-2 (myeloid differential protein-2) pathway, which leads to the upregulation of CXCR7, and ultimately tumor growth and metastasis." (PMID 32098047, 2020). "Gastric cancer cell-derived EXOs carry HMGB1 and promote the migration of gastric cancer cells by inducing neutrophil autophagy through TLR4/NF-κB." (PMID 32551121, 2020). "In gastric cancers, studies have shown that TLR4 is not only overexpressed in gastric epithelia but also upregulated in monocytes/macrophages of superficial gastritis." (PMID 33217986, 2020). "In MKN28 and MKN45 gastric cancer cells H. pylori LPS stimulation markedly upregulated the TLR4 expression and enhanced the IL-8 production, leading to an increase in cell proliferation." (PMID 33217986, 2020). "From the current background, TLR4 stimulation is a double-edged sword, so more researches should be done on gastric cancer patients, and then search for the balance of anti-tumor and pro-tumor in the future." (PMID 33469538, 2020).
gastric cancer (continued). "In gastric cancer, TLR4 is the recognition receptor of helicobacter pylori LPS on gastric epithelial cells." (PMID 33469538, 2020). "Li and colleagues verified that LPS activated TLR4/MD-2 signaling pathway through the induction of CXCR7 expression to promote gastric cancer proliferation and migration." (PMID 32014008, 2020). "We investigated the mRNA and protein expression levels of TLR4 and MD-2 in human gastric cancer cell lines (SGC-7901, AGS, MGC-803, BGC-823 and MKN-45) and normal gastric epithelial GES-1 cells using RT-PCR and western blotting." (PMID 30636642, 2019). "LPS can upregulate CXCR7 expression through TLR4 signaling, thereby promoting gastric cancer cell proliferation and migration." (PMID 30636642, 2019). "Nevertheless, the biological function and regulation of CXCR7 and its relationship with TLR4 and MD-2 in gastric cancer are not completely understood and therefore warrant further study." (PMID 30636642, 2019). "Related research found that TLR4 is upregulated in gastric cancer tissues and has low expression in normal gastric mucosa." (PMID 30636642, 2019). "The results showed that the mRNA and protein expression of both TLR4 and MD-2 was higher in gastric cancer lines than in normal gastric epithelial GES-1 cells." (PMID 30636642, 2019). "In the present study, we explored the function of CXCR7 in the LPS/TLR4/MD-2 regulatory pathway in gastric cancer." (PMID 30636642, 2019). "On the other hand, TLR4 rs4986791 as well as TLR9 rs5743844 SNPs though have MAF <0.05, were selected as these polymorphisms have previously been shown to be associated gastric cancer (TLR4) and CpG oligonucleotide hyporesponsiveness (TLR9)." (PMID 31365550, 2019). "Toll-like receptor 4 (TLR4) and myeloid differential protein-2 (MD-2) are also reported to be involved in gastric cancer cell proliferation and invasion." (PMID 30636642, 2019). "To investigate the susceptibility and prognostic value of genetic variations of IL-16, TGFBR1 and TLR4 pathways to gastric cancer, we performed a case–control study combined a retrospective study in a Chinese population." (PMID 30479570, 2018). "Gastric cancer cell-derived exosomes induced autophagy in neutrophils by activating NF-κB pathway through HMGB1/TLR4 interaction." (PMID 30292233, 2018). "TLR4 inhibitor decreased the expression of inflammatory factors in GC-Ex-treated neutrophils and impaired its gastric cancer cell migration-promoting effect." (PMID 30292233, 2018). "We concluded that two polymorphisms (rs334348, rs10512263) in TGF-BR1 were associated with risk of gastric cancer, and that TLR4 rs1927911 and TGFBR1 rs10512263 were associated with clinical outcomes of gastric cancer patients." (PMID 30479570, 2018). "Gastric cancer cell-derived exosomes carried high mobility group box-1 (HMGB1) that interacted with toll-like receptor 4 (TLR4) to activate NF-κB and induce autophagy in neutrophils, which in turn promoted gastric cancer cell migration." (PMID 30292233, 2018). "In the retrospective study, we observed TLR4 rs1927911 and TGFBR1 rs10512263 were associated with clinical outcomes of gastric cancer patients." (PMID 30479570, 2018). "Moreover, methylation of the TLR4 promoter is associated with TLR4 silencing in a variety of cells, including intestinal epithelial and stem-cell–derived vascular cells, but the precise epigenetic mechanism underlying progression of gastric cancer is not fully understood." (PMID 26675260, 2016). "Here, we investigated the mechanism underlying regulation of TLR4 expression through promoter methylation and histone modification between transcriptional regulation and silencing of the TLR4 gene in gastric cancer cells." (PMID 26675260, 2016). "Understanding the precise mechanism of TLR4 regulation is important to understanding the development and progression of gastric cancer." (PMID 26675260, 2016).
gastric cancer (continued). "Recently, TLR4 is highly expressed in a stage-dependent manner in gastric cancer, but the regulatory mechanism of TLR4 expression has been not elucidated it." (PMID 26675260, 2016). "Reactive oxygen species (ROS) were involved in TLR4-triggered immune response and gastric cancer progression." (PMID 27286259, 2016). "We next examined TLR4 mRNA level in eight gastric cancer cell lines using qPCR and reverse transcription-PCR." (PMID 26675260, 2016). "Although the expression of TLR4 in gastric cancer cells has been examined, the mechanisms and the molecular pathways mediated by TLR4 signaling in gastric tumorigenesis are still controversial." (PMID 26675260, 2016). "In this study, our results suggested that TLR4 expression in gastric cancer correlated with tumor stages and difference of TLR4 expression related to epigenetic modification via DNA methylation." (PMID 26675260, 2016). "Individual genetic effects of 13 single nucleotide polymorphisms (SNPs) in PGC, PTPN11, TLR4, and IL1B on the susceptibility to gastric cancer and atrophic gastritis have been reported in our previous studies." (PMID 26158864, 2015). "Many recent studies have demonstrated the critical role of TLR4 in the inflammatory-related immune response to H. Pylori infection in the pathogenesis of gastric cancer." (PMID 25290654, 2014). "Our findings provide evidence of the molecular mechanisms of SDF-1 expression and its secretion by resistin via a TLR4-dependent pathway in gastric cancer cells." (PMID 24929539, 2014). "We found that treatment of gastric cancer cells with resistin resulted in the activation of signaling pathways mediated by TLR4." (PMID 24929539, 2014). "Further studies are required to explore the potential role of the resistin/ TLR4 axis as an effective therapeutic agent against gastric cancer." (PMID 24929539, 2014). "Human gastric cancer cells express TLR4, TLR5, and TLR9, whereas human laryngeal cancer cells express TLR2, TLR3, and TLR4." (PMID 25360699, 2014). "Accordingly, recent evidence has demonstrated that TLR4 signaling induce mitochondria ROS production, contributing to the gastric cancer progression." (PMID 25136295, 2014). "Association between TLR2, TLR4 and CD14 polymorphisms and risk of gastric cancer in ethnic Chinese individuals." (PMID 23565226, 2013). "Individual studies included in the meta-analysis of TLR2, TLR4 and CD14 polymorphisms and gastric cancer." (PMID 23565226, 2013). "Effect of Helicobacter pylori infection and TLR2, TLR4 and CD14 polymorphisms on gastric cancer risk." (PMID 23565226, 2013). "Recently, a functional polymorphism of the TLR4 gene, associated with impaired TLR signalling, was considered as a significant risk factor for gastric carcinoma." (PMID 18775079, 2008). "However, in another study, the expression of TLR1, TLR2, TLR4, TLR5 and TLR6 was associated with survival in gastric cancer, and only high cytoplasmic TLR2 expression was shown to be significantly associated with a poorer 5-year survival." (PMID 40362298, 2025). "Studies indicate that gastric cancer patients with high TLR4 expression may require more intensive or individualized treatment regimens to overcome resistance to chemotherapy." (PMID 39451226, 2024). "In gastric cancer TLR4 and TLR5 activation induced cancer cell survival." (PMID 38709790, 2024). "TLR4 expression gradually increased in normal gastric cardia tissues, cardiac inflammation, and GC cells; TLR4 expression was found to be more abundant in gastric cancer tissues compared with normal control tissues that were adjacent to the cancerous tissues." (PMID 38685971, 2024). "However, it does align with studies that have found protective effects of TLR4 SNPs in certain cancers, such as hepatocellular carcinoma and gastric cancer." (PMID 39684439, 2024).
gastric cancer (continued). "Exosome transporter high-mobility group box 1 (HMGB1) derived from gastric cancer cells induces neutrophil autophagy via the HMGB1/Toll-like receptor 4 (TLR4)/nuclear factor-κB (NF-κB) signaling pathway, releasing pro-tumor cell migration factors, such as IL-1β and OSM." (PMID 38760815, 2024). "Compared with those in the naloxone group, the expression levels of TLR4 (P < 0.05) in gastric cancer tissue in the naloxone group were greater; however, the expression levels of IL-6 (P < 0.01) and TNF-α (P < 0.01) in the naloxone group were greater than those in the nonnaloxone group." (PMID 38720250, 2024). "Therefore, these predicted herbs and herbal ingredients have great potential to improve the prognosis of gastric cancer patients by acting on the targets TLR4 and KRAS, and provide alternative options and direction for anti-gastric cancer herbal research." (PMID 36936437, 2023). "Interestingly, H. pylori can even directly promote the growth of gastric cancer through the LPS–TLR4 pathway, and vice versa, the neutralization of TLR4 can suspend this proliferative activity." (PMID 37047625, 2023). "Caucasian population-based case-control study data suggest that the TLR4 + 896A > G polymorphism is a risk factor for non-cardia gastric carcinoma and its precursors." (PMID 37370894, 2023). "Furthermore, it has been proven that H. pylori LPS promotes the proliferation of gastric cancer cells via the TLR4 pathway." (PMID 34436224, 2021). "TLR4 was highly expressed in gastric cancer cells related to the aggressiveness of gastric cancer." (PMID 33469538, 2020). "Furthermore, Sophoridine also polarized tumor-associated macrophages (TAMs) to M1-TAMs through TLR4/IRF3 axis and thus enhanced the cytotoxic function of CD8+ T cells in gastric cancer microenvironment in a recent report." (PMID 32571331, 2020). "Given that H. pylori-derived LPS may stimulate gastric cancer cell proliferation via TLR4-IL-8 signaling H. pylori infection may also directly stimulate the proliferation and invasion of gastric cancer cells through the CagA-MET pathway." (PMID 33217986, 2020). "H. pylori LPS may bind to and activate the TLR4 signaling pathway in MNCs and further suppress T cell-mediated cytotoxicity against gastric cancer cell proliferation." (PMID 33217986, 2020). "Regarding the gastric cancer cell-derived exosomes, they could regulate pro-tumor activation (polarization) of neutrophils via autophagy as well as HMGB1/TLR4/NF-κB signaling pathway induction which promoted proliferation and migration of gastric cancer cells." (PMID 32765827, 2020). "Moreover, LPS stimulation induced CXCR7 expression in gastric cancer via TLR4/MD-2 signaling to promote the proliferation and migration of SGC7901 cells." (PMID 30636642, 2019). "In addition, we found that a high expression of TLR1, TLR2, TLR4, TLR5, TLR7, and TLR9 associated with an intestinal-type gastric cancer and with a high expression of all other TLRs." (PMID 31467388, 2019). "Therefore, in this study, we aimed to explore the tissue expression of TLR1, TLR2, TLR4, TLR5, TLR7, and TLR9 as potential prognostic biomarkers in gastric cancer patients, and to examine their associations with several clinicopathological variables." (PMID 31467388, 2019). "Furthermore, our analysis of gastric cancer tissues from 150 patients showed that CXCR7 expression is positively correlated with that of TLR4 and MD-2 and that these three factors predict a worse prognosis and poorer survival." (PMID 30636642, 2019). "TLR4 is upregulated in many solid tumors, including gastric cancer." (PMID 30636642, 2019). "Among them, it has to be emphasized polymorphisms in genes involved in the adaptive immune response such as the IL-1β cytokine and in members of the host’s innate immune response, Toll-like receptor-4 (TLR-4), which are associated with increased risk of gastric cancer." (PMID 30630444, 2019).
gastric cancer (continued). "Additionally, we established a nude mouse xenograft model to further assess the function of the LPS/TLR4/CXCR7 pathway in gastric cancer." (PMID 30636642, 2019). "The relationship between TLR4 and gastric cancer has been well studied." (PMID 29670922, 2018). "In conclusion, we demonstrate in this study that gastric cancer cell-derived exosomes induce autophagy and pro-tumor activation in neutrophils through the HMGB1/TLR4/NF-кB signaling pathway, which finally promotes the proliferation and migration of gastric cancer cells." (PMID 30292233, 2018). "Widespread maladies (e.g., Helicobacter pylori infection and gastric cancer) may chronically induce infection and inflammation and subsequently activate TLR4." (PMID 29228570, 2017). "TLR4 is expressed in gastric cancer presumably in a stage-dependent manner." (PMID 28350359, 2017). "Interestingly, TLR4 mRNA expression was overwhelmingly low levels in all gastric cancer cell lines and high level in SNU-668, AGS, and SNU-216." (PMID 26675260, 2016). "Next, to elucidate whether TLR4 activation induced by 5-aza-dC and LPS affects NF-κB signaling, we investigated the effect of combined pretreatment with 5-aza-dC and LPS in gastric cancer cell lines expressing low and high levels of TLR4." (PMID 26675260, 2016). "In these results, we found that TLR4 expression was frequently upregulated in human gastric cancer tissues and cells such as AGS, SNU-216 and SNU-668, but was often downregulated in several gastric cancer cell lines such as NCI-N87, SNU-620, SNU-638, NUGC3 and MKN74." (PMID 26675260, 2016). "Therefore, we investigated the effect of 5-aza-dC on promoter methylation and of 5-aza-dC and TSA on expression of TLR4 in gastric cancer." (PMID 26675260, 2016). "We used qMSP to assess the extent of methylation of the TLR4 promoter in gastric cancer cell lines expressing low levels of TLR4 and observed that these cells showed high levels of DNA methylation compared with SNU-668 cells, which express a high level of TLR4." (PMID 26675260, 2016). "This in silico data suggest that TLR4 expression may be regulated by an epigenetic mechanism, and we hypothesized that TLR4 expression may be silenced by promoter methylation in gastric cancer cell lines." (PMID 26675260, 2016). "Furthermore, we confirmed TLR4 mRNA level in 15 pairs of gastric cancer tissue and adjacent normal tissue using quantitative PCR (qPCR) and found 5-fold enhancement in gastric cancer tissues (p < 0.0016)." (PMID 26675260, 2016). "Interestingly, it was reported that H. pylori LPS can promote proliferation and progression of gastric cancer cells via a TLR4-dependent pathway as well as to attenuate cytotoxicity of PBMCs and thus promote cancer formation." (PMID 25945326, 2015). "In a case-control study and meta-analysis, Castaño-Rodríguez and coworkers reported that the TLR signaling pathway was implicated in gastric carcinogenesis, with TLR4 Asp299Gly and TLR2 −196 to −174 del showing associations with gastric cancer in an ethnic-specific manner." (PMID 25945326, 2015).